ALDH3A1 (aldehyde dehydrogenase 3 family member A1)
Diseases named in the same sentence as ALDH3A1 in open-access papers (continued):
Sharing a sentence is not in itself a finding about the gene and the disease.
infection (3 papers, 2013 to 2021). The state of being infected such as from the introduction of a foreign agent such as serum, vaccine, antigenic substance or organism. "The baculovirus infection system in Sf9 cells in combination with 5′ AMP sepharose chromatography resulted to extremely high yield of recombinant ALDH3A1 with sufficient solubility." (PMID 23451057, 2013). "At these conditions only one gene was detected as significantly up-regulated after infection, NLRP2, and four genes were down-regulated (ALDH3A1, CXCL8, IL1R2, KRT15)." (PMID 34785679, 2021).
gastrointestinal tumors (1 paper, 2015). "The 3A1 isoenzyme, is also involved in the detoxification of Cyclophosphamide (CP) and high ALDH3A1 values may be one of the reasons why CP is ineffective against gastrointestinal tumors but effective against tumors that exhibit low 3A1 expression profiles." (PMID 26580399, 2015).
neurodegenerative disease (1 paper, 2021). A disorder of the central nervous system characterized by gradual and progressive loss of neural tissue and neurologic function. "However, the role of ALDH3A1 in neurodegenerative diseases has not been reported." (PMID 33597859, 2021).
ALDH3A1 also shares sentences with these, for which no sentence is quoted: adenocarcinoma (4 papers); leukopenia (2); adenoma (1); atherosclerosis (1); bacterial infection (1); chordoma (1); corneal opacities (1); dry eye (1); gastric adenocarcinoma (1); gout (1); hemorrhagic cystitis (1); hepatocellular adenoma (1); intervertebral disc degeneration (1); Liver toxicity (1); lung fibrosis (1); meningioma (1); neutropenia (1); Obesity (1); Onset (1); peripheral neuropathy (1); pneumonia (1); retinopathy (1); rheumatoid arthritis (1); schizophrenia (1); skin cancer (1); small cell lung carcinoma (1); toxicity (1).